CTLA4 (cytotoxic T-lymphocyte associated protein 4)
Diseases named in the same sentence as CTLA4 in open-access papers (continued):
Sharing a sentence is not in itself a finding about the gene and the disease.
tumor (continued). "Dual ICI with anti-CTLA-4 and anti-PD-1 was tested in a similar autologous PBMC intraperitoneal EOC PDX model with a significant reduction in tumor volume." (PMID 35804867, 2022). "Critically, tumor-infiltrating TRM express immune checkpoint molecules including PD-1, CTLA-4, and LAG-3." (PMID 36466880, 2022). "IL‐6 targeting along with anti‐CTLA‐4 therapy has been found to reduce M2 cells and PD‐1+ CD8+ T cells and further improved the survival of tumor‐bearing mice." (PMID 35301813, 2022). "In comparison, ICG-PDT in combination with CTLA4 antibodies loaded P407 hydrogel injection in situ cocktail exhibited effective tumor suppression and moderate percentage of tumor ablation in MC38 tumor-bearing mice." (PMID 35974207, 2022). "Immune checkpoint inhibitors (including PD-1, CTLA-4, PD-L1, and TIM-3) reduced the activation of immune cell, leading to immunosuppression of the tumor immune microenvironment." (PMID 35774794, 2022). "Expression of immune checkpoint proteins restrict immunosurveillance in the tumor microenvironment; thus, FDA-approved checkpoint inhibitor drugs, specifically PD-1/PD-L1 and CTLA-4 inhibitors, promote a cytotoxic antitumor immune response." (PMID 35011741, 2022). "Specifically, activated Treg cells destroy tumour immunity by enriching a series of costimulatory molecules (such as ICOS, CD27, 41BB, OX40, and GITR) and immune checkpoints (PD-1, CTLA-4, LAG3, and TIGIT) to promote tumour immune evasion." (PMID 36110969, 2022). "CTLA4 and OX40L exhibited similar trends to each other, with overexpression in tumor tissue leading to reduced time to relapse, but overexpression in TAS leading to increased time to relapse." (PMID 36230846, 2022). "CTLA4 and PD1 play an important role in tumorigenesis and tumor immune tolerance and have been proved to be prognostic biomarkers for various cancer types." (PMID 35444953, 2022). "Immune checkpoint molecules (PD-L1, CTLA-4, and PD1) inhibit the activity of T cells in the tumor microenvironment, thereby suppressing anti-tumor immunity-associated processes." (PMID 35372377, 2022). "CTLA-4 gene is expressed in a variety of cells, including B cells, monocytes, granulocytes, CD34+ stem cells, and various tumor cells." (PMID 36147250, 2022). "Certain positive regulatory factors, such as CD27, CD28, CD30, ICOS, and negative regulatory factors, such as CTLA4, PD-1, BTLA, TIM3, andLAG3, at immune checkpoints affect the recognition and apoptotic ability of the immune system against tumour cells." (PMID 36118669, 2022). "Moreover, preclinical studies found that radiation delivered as single high dose of 20 Gy could impair tumour immunogenicity, whereas fractionated radiotherapy could stimulate anti‐tumour immunity and demonstrated effective abscopal responses when combined with anti‐CTLA‐4 antibody." (PMID 35466515, 2022). "Long-acting repeatable of SSA decrease the level of total regulatory T cells and MDSCs, as well as the expression of PD1, CTLA4 and ENTPD1 in neuroendocrine neoplasms which exert an anti-tumor immunosurveillance function." (PMID 36072337, 2022). "Using a broad collection of immune gene sets, we found that IED states correlated with lymphoid cells, CD8+ T cell and NK cell infiltration, the tumor inflammation signature score, and immune checkpoints TIGIT, CTLA4, and PD-L1." (PMID 36099049, 2022). "Dr. Allison showed that the CTLA-4 monoclonal antibody blocked CTLA-4 function, which enhanced anti-tumor immunity and led to a cure for cancer in mouse models." (PMID 35628647, 2022). "Another group has developed a chimeric heavy-chain antibody targeting cells expressing CTLA-4, such as Tregs and CD4 helper T cells, and reported an induction of the cytokine IFN-γ, whose pleiotropic actions include anti-tumor activity." (PMID 36686160, 2022).
tumor (continued). "In mouse tumor models, the combined application of a GITR antibody and a CTLA‐4 antibody results in 80% tumor inhibition, reduction of intra‐tumoral Treg (via GITR), and stimulation of CD8+ T cells (via CTLA‐4)." (PMID 35674216, 2022). "1.Reduce TAM and induced residual TAM to polarize M2 phenotype, increase the level of tumor-infiltrating lymphocytes.2.Increased PD-1/PD-L1 expression on TAM and CTLA-4 expression on CD8+ T cells." (PMID 35874717, 2022). "We show that VEGF expression, for example, is enriched in the tumor parenchyma compared with the stroma; VEGF signaling has been found to promote PD-1, CTLA-4, TIM-3, and TOX expression on CD8+ T cells." (PMID 35584630, 2022). "SIGLEC15, PDCD1LG2(PD-L2), TIGIT, PDCD1(PD-1), CD274(PD-L1), CTLA4, LAG3, and HAVCR2(TIM3) are immunological checkpoints that perform a vital function in tumor immune evasion." (PMID 35840882, 2022). "Nevertheless, new studies suggest that CTLA4 blockade within the tumor microenvironment could decrease the activation threshold of T cells, while selectively depleting immunosuppressive regulatory T cells; these effects increase the number of tumor-specific CD8 T cells." (PMID 35493449, 2022). "CTLA4 primarily functions by indirectly diminishing signaling through the co-stimulatory receptor CD28, reducing immune responses to weaken self- and tumor antigens." (PMID 35330161, 2022). "We found that CSF-1R was significantly correlated with tumor-related immunosuppressive molecules including PDCD1, CTLA4, CD80, CD86, HAVCR2, etc.." (PMID 35444953, 2022). "As previously noted in the portal blood, T cells found in the portal blood tumor microenvironment and in PortalBMC grown ex vivo are found in a highly anergic state (CD25+CTLA4+PDL1+PD1+CD45+CD3+)." (PMID 35316296, 2022). "The significant correlation between DDR1 and regulatory T cells and T-cell exhaustion markers such as TGFβ1, PD-1, and CTLA-4 indicated that DDR1 was involved in immune escape and tumor invasion." (PMID 35935941, 2022). "Particularly, the emergence of immune checkpoint inhibitors (ICIs, such as CTLA-4 and PD-1/PDL-1 inhibitor) and adoptive cell therapy (chimeric antigen receptor T cells, CAR-T) represents a turning point for tumor treatment." (PMID 35155237, 2022). "Furthermore, finding the proper combination such as combined with immunotherapies (such as anti-PD1, anti-PD-L1, and anti-CTLA4), targeting drugs, chemotherapies etc. may be the best approach to increase the anti-tumor effectiveness of GSK126 and other EZH2 inhibitors." (PMID 35432300, 2022). "We used the tumor immune dysfunction and exclusion (TIDE) algorithm to assess the effects of GPR87 on the response rates to immune checkpoint (PD-1 and CTLA-4) inhibitors." (PMID 35790819, 2022). "Most of the tumor immunity-related genes, including PD-L1 (CD274), PD-1 (CD279), CTLA4, and B7H3 (CD276), were at a higher expression level in the high-risk group." (PMID 36267281, 2022). "LncRNA TCL6 is related to tumor infiltrating lymphocytes and immune checkpoint molecules including PD1, PDL1 and CTLA4." (PMID 35372082, 2022). "A significant decrease was seen in the number of circulating and tumor-infiltrating FOXP3+ and stromal CTLA-4+ T cells." (PMID 35967381, 2022). "As tumor progression and immune activation were both enhanced in the high SLC11A1 group, SLC11A1 expression possibly be related to the high PD-1 and CTLA4 expression." (PMID 36531992, 2022). "Hypoxia has been shown to modulate the expression of immune checkpoints such as CTLA-4, CD47, PD-1/L-1, and TIM3 in order to manipulate immune cells’ mediated anti-tumour response, thereby inhibiting immune surveillance." (PMID 35621637, 2022). "Among tumor-infiltrating Tregs, investigators detected T-bet+Foxp3+CD4+ T cells with a higher expression of typical Treg factors, such as ICOS, GITR, CD103, CTLA4, PD-1, and IL-10 as compared to CD4+ T cells, which express either T-bet or Foxp3." (PMID 35626725, 2022).
tumor (continued). "Blocking CSF-1/CSF-1R alone increased PD-1/PD-L1 expression on TAM cells and CTLA-4 expression on CD8+ T cells, whereas combination with PD-1 or CTLA-4 antagonists led to more significant T cell infiltration and tumor regression." (PMID 35874717, 2022). "PD-L1 expression of tumor antigen presenting cells and T cells was upregulated after treatment of various solid tumor arterial models with HDAC and CTLA-4 inhibitors." (PMID 35140720, 2022). "IPS and TIDE scores are novel tumor immunotherapy response rate biomarkers that better assess the efficacy of anti-PD1 and anti-CTLA4 therapies." (PMID 36467074, 2022). "Both CTLA4 and PD1 ICIs treatment can activate immune checkpoint molecules expressed on the surface of T cells, thereby reactivating T cells to play anti-tumor role." (PMID 35979350, 2022). "Here, together with anti-CTLA-4 and anti-PD-1 Abs, anti-CD73 Abs showed significant efficacy in stimulating tumor immunity in several tumor models including colon, prostate, subcutaneous tumors, and breast cancer." (PMID 35711418, 2022). "Together, these results indicate that 7HP349 has a therapeutic benefit in combination with standard CTLA-4, PD-1, or dual CTLA-4/PD-1 blockade for the treatment of cancer in murine tumor models." (PMID 35552271, 2022). "The general perception is that IC molecules, such as PD1, CTLA4, LAG3, and TIGIT, are expressed in T cells and NK cells, and the ligands are expressed in the other cells, including tumor cells and myeloid cells." (PMID 36211375, 2022). "By using monoclonal antibodies against immune checkpoints (ipilimumab against CTLA-4, or nivolumab and pembrolizumab against PD1), cancer immunotherapy effectively releases tumor-induced immune system brakes to restart cancer immune circulation." (PMID 36406133, 2022). "CTLA-4, TIM-3 and ICOS were decreased 6 weeks post-FLOT or CROSS chemoradiotherapy treatment on tumour-infiltrating T cells." (PMID 35366537, 2022). "This is in line with recent observations that anti-CTLA4 and anti-PD1 therapies target distinct tumor-infiltrating lymphocytes (TIL) populations to induce tumor rejection." (PMID 34793335, 2022). "JHU083 showed significant inhibition of 4T1 tumor growth in mice compared with vehicle, anti-PD1, anti-CTLA4 or combination checkpoint blockade." (PMID 36465373, 2022). "Because the anti-tumor effects of anti-PD1/PD-L1 and anti-CTLA-4 employ different mechanisms, the combination of these ICIs promises higher potency against various malignancies but also increases the risk of irAEs." (PMID 36447159, 2022). "As the depletion of Treg cells significantly reduces tumor burden, strategies targeting receptors (CCR4, CD25, CTLA-4, CCR8) preferentially expressed on tumor infiltrating Tregs are currently being evaluated in clinical trials." (PMID 36498469, 2022). "A similar approach was applied to dissect tumor-specific B cell proliferation networks involving PD1 (PDCD1), PDL1 (CD274), and CTLA4." (PMID 35804895, 2022). "Immune checkpoint inhibitors, such as CTLA-4 and PD1/PDL1 inhibitors, have demonstrated clinical efficacy in many tumours, which is a major breakthrough in oncology." (PMID 35510041, 2022). "TAMs also keep the immune system suppressed through the following additional pathways: regulation of PD-1 and CTLA-4, T-cell suppression and exhaustion, recruitment of Tregs through CCL2, and promotion of inflammation of the tumor microenvironment." (PMID 36358857, 2022). "It was found that autophagy inhibition using a clinically available antimalarial agent, chloroquine, increased surface levels of MHC-I and anti-tumor T cell responses when combined with ICI therapy (anti-PD-1 and anti-CTLA4)." (PMID 35296095, 2022). "PD-1 blockade prompts CD8+ T cell differentiation; CTLA-4 blockade solves restrictions on T cell priming and activation; ACT may bypass limitations on T cell priming and expansion; OV therapy mediates new T cell priming and activation by lysing tumor cells to release tumor-associated antigens." (PMID 36618408, 2022).
tumor (continued). "In tumor models, the combined use of antibodies targeting TIM-3, PD-1, and CTLA-4 has been shown to be more effective and well tolerated." (PMID 36140182, 2022). "Following the observation of tumour shrinkage in mice treated with CTLA-4 antibodies, the monoclonal antibody to CTLA-4, Ipilimumab was developed for human use." (PMID 35576080, 2022). "T cell inhibitory receptors, such as CTLA-4, PD-1, and TIGIT, are essential for limiting immunopathology and terminating effective immune responses, but also can restrain effective anti-tumor immune responses." (PMID 35263569, 2022). "Tumor cells inhibit the anti-tumor response in the TME through immune checkpoints, such as the PD-1/PD-L1 and CTLA4 pathways." (PMID 35618810, 2022). "High-dose vitamin C can decrease tumor volumes combined with anti-PDCD-1(PD-1) and anti-CTLA4 and enhance CD8+ T cell cytotoxic activity." (PMID 35600371, 2022). "We previously reported that vaccination with a CTLA4-PD-L1 DNA cancer vaccine induced endogenous antibodies against CTLA-4 and PD-L1, and inhibited the tumor growth in a spontaneous TAA-induced rat iCCA model." (PMID 36341387, 2022). "Immune monitoring affects the prognosis of tumor patients, and tumors use immune checkpoints such as PD-1, PD-L1 AND CTLA-4 to evade immune responses." (PMID 36158677, 2022). "In the tumor microenvironment, infiltrating immune cells experience functional impairment by expressing multiple inhibitory signals on the cell surface, such as PD-1/PD-L1, CTLA-4, TIGIT, and TIM-3, leading to tumor immunosuppression." (PMID 35844572, 2022). "For example, macrophages with the expression of PD-L1/PD-L2 and CD80/CD86, bind to PD-1 and CTLA4, leading to impairment of TCR signaling and suppression of cytotoxic functions of T cells, and promoting tumor evolution." (PMID 36741415, 2022). "In quantitative evaluation, the anti-tumor effects of mono and bispecific antibodies of FRG and CTLA-4 were all significant." (PMID 36618349, 2022). "They found that more interstitial CTLA-4+ lymphocytes were related to longer DFS and OS, whereas more CTLA-4+ tumor cells were related to shorter DFS and OS." (PMID 35646659, 2022). "The combination of anti-CTLA-4 antibody and anti-CD25 antibody can significantly inhibit tumor growth and progression in vivo." (PMID 35892678, 2022). "In GSE37745, except for CTLA4 and IFNG, the other genes were also significantly upregulated in hot tumor group." (PMID 35211415, 2022). "The rationale for their implementation in this setting originates from the observation that CTLA-4, PD-1, and PDL-1 are overexpressed in the tumour microenvironment, on tumour cells, and T cells intermingled with neoplastic cells." (PMID 35204486, 2022). "Improvements in local and distant tumor control and overall survival have been seen when intratumoral NDV was combined with systemic programmed cell death protein 1 (PD-1) or CTLA-4 inhibition." (PMID 36498574, 2022). "The NOT logic CAR was initially conceived by fusing the intracellular domain of PD1 or CTLA4 with a targeting domain recognizing antigens expressed on healthy tissues, thus allowing the primary tumor-targeting CAR to selectively kill tumor cells." (PMID 35720306, 2022). "Local depletion of CTLA4 expressing cells by NIR-PIT promotes the activation and infiltration of CD8+ T cells in the tumor microenvironment and prolonged survival in vivo with observation of CD8+ T cell activation and infiltration." (PMID 35884975, 2022). "The combination of anti-CTLA4 and anti-PD-L1 increased tumor-infiltrating lymphocyte function and restored HCC-derived T cell responses to tumor antigens." (PMID 36213162, 2022). "In summary, inhibitory ICs TIM-3, LAG-3, CTLA-4 and PD-L2 and stimulatory IC ICOS were significantly upregulated on tumour-infiltrating T cells compared with peripheral circulating T cells in OAC patients." (PMID 35366537, 2022).
tumor (continued). "Meanwhile, in tumor cells from INE patients, a higher expression of CTLA-4 was found concerning IE (p = 0.001)." (PMID 36358618, 2022). "Suppressive nature of Tregs in tumours is supported by the expression of CD25, PD-1 and CTLA-4 on their surface which further shapes cellular architecture of tumours in an immunological sense." (PMID 35493450, 2022). "CTLA-4 binds to its ligands B7-1 (CD80) and B7-2 (CD86) to generate inhibitory signals that suppress T cell activation and cytokine production and protect tumor cells from T cell attack." (PMID 36532071, 2022). "We recently discovered that stressed/injured but still viable tumor cells are critical for T-cell priming and substantially improve responses to systemic anti-PD1/CTLA4." (PMID 35402699, 2022). "However, since metformin activates anti-tumor immunity by different mechanisms from anti-PD-1/PD-L1 or anti-CTLA-4 mAbs, the combination of immune check point inhibitors and metformin may provoke remarkable radiosensitizing effects leading to improved outcomes in patients with LARC." (PMID 35508498, 2022). "The treatment was administered by intramuscular injection followed by electroporation in combination with anti-PD-L1 and anti-CTLA-4 ICB therapy, manifesting a potent antitumor response that increased the survival of mice in different tumor models." (PMID 36145609, 2022). "The results show that, in addition to tumor cells, in vivo HIF-1α inhibition can also suppress PD-L1 on tumor-infiltrating myeloid cells, and these effects persist in the context of anti–CTLA-4 therapy." (PMID 35239514, 2022). "We found that the high-risk group was significantly associated with higher expression level of immune checkpoints and immune inhibitory factors, including CCL2, CTLA4, CXCR4, IL6, LAG3, PDCD1, and TGFB1, indicating tumor immune evasion." (PMID 36092894, 2022). "In a different approach, NP encapsulating CTLA-4 siRNA showed a decrease in CTLA-4 expression and a suppression of tumor growth after systemic administration in a B16 melanoma mouse tumor model." (PMID 36106025, 2022). "Inhibitory receptors, in particular CTLA-4, PD-1, TIGIT, TIM3, and LAG3, impair the anti-tumor immune response." (PMID 35013519, 2022). "For example, immune checkpoint proteins (PD-L1, CTLA-4, TIM3), the main targets of immunotherapy, are present in exosomes and can promote tumor progression and metastasis." (PMID 36348319, 2022). "Next, we compared the expressions of four important immune checkpoints (PD-L1, CTLA4, IL4I1, and IDO1) between normal and tumor tissues, and between the two clusters." (PMID 35778697, 2022). "The immune-checkpoint genes PD-L1 (CD247), CTLA4, LAG3, TIM3 (HAVCR2) and IDO1 were assessed using gene expression data, with significantly higher expression of each in DDIR-positive tumours." (PMID 34728791, 2022). "PD-1 and CTLA-4 are members of the CD28 family, expressed on most immune cells, and by binding to their ligands, transmit inhibitory signals to T cells to promote tumor immune escape." (PMID 36686771, 2022). "In contrast, Ctla4 expression, a marker of exhausted T cells but also Tregs, was similar in APC and AOM/DSS tumor T cells." (PMID 35600339, 2022). "PD-1, CTLA4, LAG3, and TIM-3 are four ICPs that are frequently examined in the clinic, and inhibitors targeting these factors have shown potent tumor-killing effects in a variety of tumors." (PMID 36203873, 2022). "Tumor cell co-stimulatory or co-repressor signaling, involving genes such as CD28, CD80, CD86 and CTLA4, plays a critical role in regulating cell proliferation, differentiation and cytokine secretion." (PMID 36465397, 2022). "Recent studies reported that tumor-infiltrating CD39+ Tregs in CRC patients expressed different markers such as OX-40, CTLA-4 and ICOS, implicating their high immunosuppressive abilities in inhibiting anti-tumor immune responses." (PMID 35655158, 2022).